MYC (MYC proto-oncogene, bHLH transcription factor)
Diseases named in the same sentence as MYC in open-access papers (continued):
Sharing a sentence is not in itself a finding about the gene and the disease.
tumor (continued). "The overexpression of MYCN/MYC target genes in subtype 2 tumors, and the assignment of 10 out of 11 MYCN-amplified tumors to subtype 2 tumors (the remaining MYCN-amplified tumor being unclassified) suggest that MYCN/MYC play an important role in this subtype." (PMID 34552068, 2021). "The m5C writer NSUN2 is a direct target of MYC, a well-known regulator of tumour cell proliferation, which was first found upregulated in malignant skin tumours." (PMID 34638933, 2021). "MYC, as a well-known oncogene, plays essential roles in promoting tumor occurrence, development, invasion and metastasis in many kinds of solid tumors and hematologic neoplasms." (PMID 34658888, 2021). "The bridging integrator 1 (BIN1) adaptor protein was identified initially as a pro-apoptotic tumor suppressor that binds to and suppresses the oncogenic MYC transcription factor." (PMID 34948122, 2021). "This protein was found to play a tumour suppressor role by promoting MYC dephosphorylation and degradation in lung and breast cancer cell lines." (PMID 34445233, 2021). "The let-7 miRNA family is a well-known tumor suppressor and is responsible for the repression of several oncogenes, which include MYC, HMGA2, and CCND1." (PMID 33466455, 2021). "In this context, it is interesting to note that MYC binding motifs are enriched in neuroendocrine genes; thus, it has been proposed that MYC overexpression drives the temporal tumor cell evolution." (PMID 33562873, 2021). "In this study, we investigated the presence of HIV-1 Tat within BL tumor cells, and its ability to influence the expression of c-MYC, a transcription factor that plays a primary oncogenic role in a majority of cancers, including BL." (PMID 34277639, 2021). "Combinational treatment of mTOR (AZD8055) with either MEK (trametinib) or BRD4 (JQ1) inhibitors to EIF1AX-A113splice knock-in tumour cell lines result in reduced c-MYC and mTOR protein levels and consequent tumour size reduction." (PMID 34062862, 2021). "Using a single-cell approach, we explore sources of tumour heterogeneity longitudinally in the malignant cell compartment of Vκ*MYC tumours and characterize the relationship between subclonal genomic events and subclonal transcriptional programs." (PMID 34732728, 2021). "This suggests that whilst alternative splicing confers selective growth advantage, it also renders PDAC more vulnerable to further perturbation in splicing, similar to MYC-driven tumours." (PMID 34680285, 2021). "This combination led to complete tumor growth arrest, accompanied by a significant reduction in MYC, IRF4 (interferon regulatory factor 4) and Ikaros positive cells by immunohistochemistry." (PMID 35582389, 2021). "The inference that FTH1 is a tumor suppressor in BCa is also consistent with the observation that reduced c‐MYC and/or G9a increased the sensitivity of BCa cells to anticancer drugs." (PMID 34551213, 2021). "Another insight afforded by Vκ*MYC concerned the intriguing link between microbial gut flora and IL-17-driven tumor progression." (PMID 34149703, 2021). "A recent study reveals the scope for further clinical studies to consider a well-known tumour-related gene MYC as an effective drug target." (PMID 35053185, 2021). "Although, BH3-mimetics act to neutralise any excess pro-survival proteins present within MYC-driven tumours, thereby lowering the threshold for apoptosis induction, the mechanism by which the drugs co-operate is somewhat more complicated." (PMID 33799592, 2021). "Inactivation of MGA is frequent in human cancer, and a recent study has demonstrated that MGA functions as a tumor suppressor in murine models of lung carcinoma and in colorectal cancer organoids, partly due to the de-repression of MYC target genes." (PMID 34572909, 2021). "MYC can also regulate tumor progression by inhibiting the expression of other miRNAs, such as the let-7 miRNA family, miR-15a/16-1, miR-26a and miR-34a." (PMID 34930894, 2021).
tumor (continued). "MYC has also been shown to regulate anti-tumor immune responses through various mechanisms, such as secretion of CCL9 and IL-23, and expression of PD-L1 and CD47." (PMID 34947972, 2021). "Transactivated β-catenin forms a complex with T-cell factor/lymphoid enhancer-binding factor family members and induces many instrumental downstream genes, such as CCND1 and MYC, which promote tumour development." (PMID 34155197, 2021). "MYC gene is closely related to tumor development and treatment, and it is regarded as the most promising drug target to promote HCC immunotherapy because MYC is disordered protein and lack of available drug identification site." (PMID 35008249, 2021). "We observed a higher rate of c-MYC nuclear expression inside tumor nodules compared to corresponding tumor-adjacent areas." (PMID 35008356, 2021). "Next, the results of western blotting revealed that the protein level of MYC in the xenograft tumor tissue from overexpressing or silencing circACTN4 group was significantly increased or decreased, respectively compared with the control group." (PMID 34116677, 2021). "Several previous studies reported tumor formation by iPSCs overexpressing MYC in vitro and in vivo after transduction or transplantation, respectively." (PMID 34440750, 2021). "Elevated EPIC1 promotes tumor growth by interacting with MYC to elevate its target genes, such as CDKN1A, CCNA2 and CDC20." (PMID 33860799, 2021). "Compared to uncommitted macrophages, tumor-polarized myeloid TAMs and MDSCs were characterized by the predicted activities of c-MYC, SPI and STAT3." (PMID 34208043, 2021). "Analysis of The Cancer Genome Atlas database found that out of the tumours which displayed an 8q24 copy-number increase, 97% showed a gain of both PVT1 and MYC, while less than 1% of tumours showed an increase in copy number of MYC alone." (PMID 33499210, 2021). "c-MYC contributes to the glucose metabolic reprogramming of tumor cells by regulating the expression of different target genes." (PMID 33889549, 2021). "Based on such preliminary evidence and the rational of inhibiting pathways downstream the driving oncogene MYC, we further investigated this tumor and served as a model for this study." (PMID 34557403, 2021). "In this way, we found that a number of well-known oncogenes, including MYC and SOX9, were annotated as targets of tumor-specific SEs, while several tumor suppressor genes in LUAD, such as DLC1 and RB1, were linked to normal-specific SEs." (PMID 34001209, 2021). "Several studies have shown that diminishing MYC in vivo can elicit tumor regression, suggesting that direct therapeutic targeting of MYC will be a way to attack human malignancies." (PMID 33760847, 2021). "FISH identified 4–5 or more signals at 8q24 per nucleus in 70–76% of tumor cells in the two samples with copy gains suggestive of MYC amplification by NGS, confirming unequivocal amplification." (PMID 34445161, 2021). "For example, although both are MYC-induced mouse tumours, MYC-induced liver tumours show reduced glutamine anabolism, but MYC-induced lung tumours show increased glutamine anabolism." (PMID 33926551, 2021). "Of note, CDK9 targeting by dinaciclib in MB also mediates the degradation of the oncogenic MYC, as has already been observed in different tumour settings." (PMID 33686114, 2021). "Specifically, the Thr-58 mutation in lymphoma cells blocks MYC binding to FBW7 and, thus, proteasome-mediated MYC degradation, leading to protein accumulation and tumor progression." (PMID 33801599, 2021). "It has been confirmed that MYC, as an oncogenic transcription factor, contributes to tumor cell metabolism and increases TNBC." (PMID 34993016, 2021). "In a similar manner, LMP2A can facilitate MYC activity by enhancing the degradation of the MYC inhibitor and tumor suppressor, CDKN1B." (PMID 34066504, 2021).
tumor (continued). "For the gene results, the top five genes (ranked from 17-20 and 25) were also associated with tumor formation and prognosis, including TP73 and MYC." (PMID 33912555, 2021). "Lower expression of miR-145 has been observed in EOC cell lines and tumor tissues, and its upregulation inhibits cell proliferation and promotes apoptosis by directly repressing c-MYC." (PMID 33718147, 2021). "In our data, overexpression of CCDC80 significantly suppressed CRC cell proliferation and tumor growth and induced the expression of c-MYC." (PMID 34746152, 2021). "Oncogenic deregulation of MYC expression produces cells with the tumor phenotype during normal development." (PMID 34452555, 2021). "We next examined how the timing of MYC inactivation contributed to recurrence or complete regression by administering doxycycline either: (a) when the tumor was already large (0.8 cm3); or (b) when the tumor was small (immediately after T-ALL cell injection)." (PMID 33446671, 2021). "In the adjacent native tissues, MYC expression was very low, and the H3K27ac signal on its enhancer and eRNA were close to the background; in tumor tissues, MYC was highly expressed, accompanied by elevation of H3K27ac on its enhancer and eRNA expression." (PMID 34737287, 2021). "MiR-150, which is regulated in cell lines expressing high levels of MYC, is an important regulator of hematopoiesis that strongly inhibits cell growth and is proposed to be a tumor suppressor." (PMID 34502399, 2021). "Deletion of PRKD3 by CRISPR/Cas9 in breast cancer cell lines suppressed phosphorylation of ERK1 and c-MYC and led to reduced cell proliferation in vitro and tumor growth in vivo." (PMID 33807058, 2021). "MYC promotes tumor progression by activating cell cycle related genes and repressing cyclin-dependent kinase (CDK) inhibitors, which contributes to uncontrolled proliferation and ultimately, the development of cancers." (PMID 33541412, 2021). "Nevertheless, studies in ovarian mucinous tumors showed that positive c-MYC protein expression and distribution correlated with tumor size and tumor classification, respectively." (PMID 33718147, 2021). "For instance, eIF2α‐P post‐translationally regulates PD‐L1 expression in MYC transgenic/KRAS mutant murine tumor." (PMID 34698427, 2021). "As tumor suppressors, the Let-7 family (12 members), downregulates oncogenes such as c-MYC, k-RAS, Cyclin D1 and others." (PMID 33572600, 2021). "This latent or intrinsic tumour suppressor function of MYC, mediated by its ability to induce apoptosis has been heavily investigated." (PMID 33799592, 2021). "In previous studies, it was shown that cancer cells expressing MYC proteins modify the tumour microenvironment via the activation or inactivation of growth factors, cytokines and immune checkpoint regulators." (PMID 34847775, 2021). "To test this, we developed a MAGEA3 and MYC overexpression transposon vector (pT3-EF1a-Myc-Ires-MAGEA3) to compare the rate of tumor development against the MYC transposon vector alone." (PMID 34166362, 2021). "Disruption of the Ambra1 locus induced MYC hyperphosphorylation, leading to tumour hyperproliferation and tumourigenesis." (PMID 34445233, 2021). "Here, we apply multi‐region whole‐genome sequencing to an index case of a 4‐year‐old child whose aggressive tumour harboured high‐level, focal amplifications of MYC and CCNE1 connected by translocations." (PMID 33969640, 2021). "A significant increase was observed in the expression of LGR5 (p: 0.0002) and MYC (p: 0.002) genes in G2 stage tumor tissues (group 9) compared to the control group." (PMID 34452555, 2021). "In this study, we found HIV-1 Tat to be localized within the tumor cells of BL patients, and enhanced expression of oncogenic c-MYC in these cells." (PMID 34277639, 2021). "This factor was demonstrated to regulate proliferation in cancer cells, for instance, by regulating the activity of the tumor-promoting factor c-MYC." (PMID 34831349, 2021).
tumor (continued). "High expression of FUBP1 usually leads to upregulation of c-MYC oncogene and disorder of the fine regulation of target proteins, which is one of main molecular mechanisms of tumor pathogenesis." (PMID 34116677, 2021). "The levels of ki-67 was decreased by circRHOT1 knockdown and c-MYC overexpression rescued the levels in the tumor tissues." (PMID 34406978, 2021). "In a preclinical mouse model of ATC (ThrbPV/PVKrasG12D), JQ1 was found to effectively suppress MYC expression and attenuate MYC-mediated transcriptional programs, thereby inhibiting tumor growth and finally prolonging mice survival." (PMID 34761120, 2021). "STAT3 acts astranscriptional regulator of a variety of tumor-promoting genes such asVEGF, c-MYC, CCND1 (cyclinD1), BIRC5 (survivin), which are involved in tumor development andprogression." (PMID 33749701, 2021). "This study also revealed that Sox2 was required for tumour initiation since the co-expression of endogenous Sox2 with transduced MYC was sufficient to lead to tumourigenesis in vivo." (PMID 34445233, 2021). "MYC upregulation is detected in >40% of NSCLC cases and is related to the loss of cell differentiation and tumor progression." (PMID 34783629, 2021). "Consistently, RIP analyses with an anti-FTO antibody showed that FTO bound to MYC mRNA in the tumor cells." (PMID 33966037, 2021). "Together, these data substantiate a proposal that MYC enhances glycolysis expression and stabilizes glycolytic enzymes in order to promote tumor growth." (PMID 34556188, 2021). "In vivo experiments demonstrated that co-therapy with blocking agent of MYC signaling and chemotherapeutic drugs showed synergy in tumor suppression of TNBC." (PMID 33541412, 2021). "In that study, the authors showed that PINK1 is negatively regulated by MYC, resulting in its suppression in tumor tissues." (PMID 33888730, 2021). "Landmark studies in mice doubly transgenic for BCL-2 and MYC developed tumours much more rapidly than mice expressing either transgene alone." (PMID 33799592, 2021). "Apart from early reports on the cell-transforming capacity of v-MYC, there are multiple lines of evidence supporting the importance of deregulated MYC expression in driving tumour development and progression." (PMID 33799592, 2021). "Our mathematical model uses imaging-based measurements of tumor burden to predict the relative number of drug-sensitive and drug-resistant cancer cells in MYC-dependent states." (PMID 33446671, 2021). "All 12 cases stained positively for c-MYC in the nucleus of tumor cells in 10 of 12 cases, the cytoplasm of tumor cells in nine of the 12 cases, the nucleus of stromal cells in nine of the 12 cases, and the cytoplasm of stromal cells in six of the 12 cases." (PMID 34685477, 2021). "Further, the intensity of c-MYC immunohistochemical staining in xenograft tumor sections from shRCN1 mice was significantly weaker than that in sections from shNC mice." (PMID 34663798, 2021). "An example is linc00261, which acts as a tumour suppressor in pancreatic cancer via transcriptional regulation of MYC expression." (PMID 34445233, 2021). "Another study demonstrated that in tumor cells SLC7A5 can regulate the expression of c-MYC, forming a mechanism that connects essential amino acid transport and tumorigenesis." (PMID 34977008, 2021).
tumor (continued). "It was suggested that a panel of chemokines and cytokines upregulated in MYC overexpressing cells, including MIF, IL24, CCL4, CCL3, CXCL2, or CXCL3, contributes to the recruitment of pro-metastatic tumor-associated macrophages." (PMID 34637026, 2021). "High MYC expression in tumor cells of MM patients has been shown to corelate with poor prognosis, suggesting the correlation of low NCOR2 and poor prognosis." (PMID 34864816, 2021). "According to a recent study, MYC can act as a master regulator for NE-differentiation and can dynamically shift tumor phenotype acting on the NOTCH signaling pathway from ASCL1 + NEUROD1+ (NE-high) to YAP1+ or POU2F3+ (NE-low)." (PMID 34200100, 2021). "Through transcriptional upregulation of SQLE, a rate-limiting enzyme in cholesterol synthesis pathway, MYC increases cholesterol production and promotes tumor cell growth." (PMID 33791309, 2021). "Studies have pointed that direct MYC inhibition brings about prompt tumor regression, highlighting the importance of this approach." (PMID 34372899, 2021). "Our analysis showed that the highly malignant stages of LUAD correspond to higher MYC expression levels (p = 0.0276), and a high MYC expression is associated with LUAD tumor metastasis and a larger tumor diameter (p = 0.0225)." (PMID 33540574, 2021). "c-Myc (MYC) is an oncogenic transcription factor that facilitates tumor proliferation in part through the regulation of metabolism." (PMID 34471141, 2021). "These miRNAs were transcriptionally repressed by MYC, as previously shown in a B-cell lymphoma mouse model, while miR-34a-5p possessed the most tumor-suppressive properties." (PMID 33806113, 2021). "As low as two-fold decrease in MYC expression can lead to tumor reversion in a cell-specific manner." (PMID 33958005, 2021). "Further, analysis revealed that glycolysis inhibition delayed tumor growth in a MYC-expressing xenografts." (PMID 34556188, 2021). "According to the mechanism proposed in this study, MYC amplification triggers copy number variation resulting in amplifications of other genes, including MCL1, which cooperates with MYC in sustaining tumour growth." (PMID 34389725, 2021). "Numerous downstream effectors of EGFR signaling bypassing activated KRAS and promoting tumor progression have been identified, including NFATc1 and c-MYC." (PMID 34070180, 2021). "JQ1 markedly inhibited tumor cell proliferation through G0/G1 cell cycle arrest by suppressing MYC and inducing p21, p27, and RB dephosphorylation." (PMID 34761120, 2021). "This was accompanied by reduced T-cell infiltration, supporting opposing roles of the SMAD and MYC pathways in shaping tumor immunogenicity." (PMID 33674596, 2021). "On the other hand, NEDD4 inhibits tumor proliferation by binding to MYC, inhibiting HER3 expression, and targeting PIP5K1A." (PMID 34458018, 2021). "Deregulated MYC expression is a common event in tumour cells indicating that this is an essential step in tumourigenesis." (PMID 33799592, 2021). "Overall, these findings are strong evidence that GLS1 is essential for the optimal tumorigenesis, tumor progression, and cancer cell proliferation driven by the MYC oncogene." (PMID 34503295, 2021). "Generally, it is postulated that MYC creates a positive auto-regulatory circuit, which is essential for sustaining mutual high expression in tumor cells." (PMID 33925297, 2021). "A significantly decreased tumor volume was observed only after the injection of MYC-targeting sgRNA/Cas9-loaded anti-CD19-CAR-EVs." (PMID 34199901, 2021). "The comparable lncRNA expression levels between healthy cerebella and MYC-inhibited D283 MED cells (OMO+) confirms that, at least in part, MYC is responsible for their deregulation in tumor cells." (PMID 34359754, 2021).